GOLGA6L24 (golgin A6 family like 24)
Synonyms: GOLGA6L24P
Tractability: No criterion of Open Targets' tractability assessment is met for any kind of drug.
Gene: Protein-coding gene on chromosome 15 (28,347,851 to 28,358,084, reverse strand). Ensembl gene ENSG00000237850.
Genetic constraint (gnomAD): Loss-of-function variants: 3 observed, 6.39 expected, observed/expected ratio (o/e) 0.47, 90% interval 0.21 to 1.21. That is too few expected variants to judge how well the gene tolerates losing a copy. Missense variants: 14 observed, 32.54 expected, observed/expected ratio (o/e) 0.43, 90% interval 0.28 to 0.67. Synonymous variants: 4 observed, 10.87 expected, observed/expected ratio (o/e) 0.37, 90% interval 0.18 to 0.84.
Homologues: Paralogues in human: GOLGA6L25 (99% identical), GOLGA6L22 (98% identical), GOLGA6L6 (80% identical), GOLGA6L1 (73% identical), GOLGA6L26 (73% identical), GOLGA6L2 (39% identical), GOLGA6L7 (35% identical), GOLGA6L4 (17% identical), GOLGA6L10 (16% identical), GOLGA6L9 (16% identical).